INS (insulin)
Diseases named in the same sentence as INS in open-access papers (continued):
Sharing a sentence is not in itself a finding about the gene and the disease.
maturity-onset diabetes of the young type 3 (3 papers, 2011 to 2017). Monogenic diabetes caused by inactivating mutation(s) in the gene HNF1A, encoding hepatocyte nuclear factor 1-alpha. "Maturity-onset diabetes of the young type-3 (MODY3) is an early onset, non-insulin-dependent form of diabetes characterized by autosomal-dominant inheritance." (PMID 24647409, 2014). "While the HNF1A G319S polymorphism demonstrated reduced in vitro capacity to transactivate insulin response, this disorder was not as severe as that seen in some nonsense mutations in HNF1A that underlie MODY type 3." (PMID 21208426, 2011).
Men (3 papers, 2018 to 2024). "Men with (20 T2D) and without T2D (12 insulin-sensitive, IS-NDM; 10 insulin-resistant, IR-NDM) underwent hyperinsulinemic-euglycemic clamps, spiroergometry, ectopic lipid quantification and muscle biopsies at baseline, after 12-week HIIT and after 4-week detraining." (PMID 39626509, 2024).
monogenic diabetes (3 papers, 2018 to 2025). "Monogenic diabetes is rare and arises from mutations in one of about a dozen genes, including the insulin gene and genes downstream of insulin action, such as glucokinase." (PMID 35455074, 2022).
nematode infection (3 papers, 2020 to 2025). "Even though the interplay between Toll and insulin signaling in the absence of infection is evident, interaction between the two pathways is not observed in the context of parasitic nematode infection." (PMID 37251825, 2023). "Additionally, significant enrichment was observed in the metabolic and signaling pathways, such as glycosaminoglycan degradation, insulin secretion, VEGF signaling, and apoptosis pathways, highlighting their roles in the regulation of immune response and cell survival during nematode infection." (PMID 40429216, 2025).
nephritis (3 papers, 2022 to 2024). Inflammation of renal tissue. "Specifically, Methotrexate and Insulin products emerged as potential high-risk factors for various forms of nephritis." (PMID 38765814, 2024).
neuroendocrine carcinoma (3 papers, 2017 to 2025). A malignant neuroendocrine neoplasm composed of cells containing secretory granules that stain positive for NSE and chromogranin. "Thus, these cell lines qualify better for a neuroendocrine carcinoma subtype with ectopical insulin production, rather than a faithful model for human INS." (PMID 34794032, 2021).
Obesity Syndromes (3 papers, 2016 to 2023). "Amongst the international registries identified, several existed for discrete groups of conditions including Adrenal, Genetic Disorders of Glucose and Insulin Homeostasis and Growth and Obesity Syndromes." (PMID 30407922, 2019). "A positive correlation was observed between lipid hydroperoxide (LOOH) and levels of IL-15, TNFα, insulin, total cholesterol, LDL, and triglycerides in normal-weight obese syndrome patients." (PMID 38140309, 2023). "In keeping with an euglycemic obesity syndrome, mice in the CAF group exhibited no significant change in serum glucose and significantly greater serum insulin concentrations compared to corresponding values in the CAC group at the end of both the weight loss and weight regain phases." (PMID 26784324, 2016).
obstructive lung disease (3 papers, 2021 to 2024). "This mechanical effect aggravates airway obstruction, leading to breathing difficulties and intermittent hypoxia, which in turn worsens insulin resistance and inflammation, forming a self-perpetuating cycle." (PMID 39737149, 2024). "A second logistic model confirmed the general protective effect of aspirin, except those individuals taking both aspirin and insulin had a nearly two-and-a-half-fold increase in the odds of obstructive lung disease." (PMID 35969698, 2022). "This adjusted model showed increased odds of having obstructive lung disease when insulin and aspirin are taken together." (PMID 35969698, 2022). "The use of insulin was not strongly associated with obstructive lung disease in univariate analysis and was not included in the multivariate model." (PMID 35969698, 2022). "In other words, aspirin enhances insulin action, which could lead to obstructive lung disease." (PMID 35969698, 2022).
opioid use disorder (3 papers, 2022 to 2026). A substance-related disorder that involves the recurring use of opioids despite negative consequences. "Opioid use disorder (OUD) has been linked to cardiometabolic diseases in adults through reductions in adiponectin-an adipocytokine with insulin-sensitizing effects." (PMID 41993904, 2026).
optic neuropathies (3 papers, 2024 to 2026). "Optic neuropathy may be caused by poor metabolic control and a sudden tightening of blood sugar (for example, during pregnancy, and after insulin therapy)." (PMID 40537689, 2025). "No previous trials have tested the safety and efficacy of topical human recombinant insulin in human subjects with optic neuropathies." (PMID 41584099, 2026).
overactive bladder (3 papers, 2012 to 2024). Symptom of overactive detrusor muscle of the urinary bladder that contracts with abnormally high frequency and urgency. "Through our research, we found white blood cells and neutrophils mediated the correlation between glucose, fasting glucose, and insulin and an overactive bladder." (PMID 38745959, 2024). "The present study shows that high-fat fed obese mice display overactive bladder and enhanced PKC protein expression in bladder tissues that are normalized by blockade of Cav1.2 and improvement of insulin sensitivity." (PMID 23144896, 2012).
overgrowth syndrome (3 papers, 2020 to 2025). A group of syndromes caused by genetic birth defects that may lead to the development of malignancies. "One other human overgrowth syndrome that eventually leads to IR, T2D and higher mortality rates, which also implicates excessive insulin/IGF signaling and insulin/IGF resistance, is acromegaly." (PMID 40055326, 2025).
periodic paralysis (3 papers, 2011 to 2016). "Insulin also may activate Na+/K+ATPase activity, which explains the correlation between periodic paralysis and high-carbohydrate meals." (PMID 25484903, 2014).
permanent neonatal diabetes mellitus (3 papers, 2013 to 2024). Permanent neonatal diabetes mellitus (PNDM) is a monogenic form of neonatal diabetes (NDM) characterized by persistent hyperglycemia within the first 12 months of life in general, requiring continuous insulin treatment. "Permanent neonatal diabetes mellitus (PNDM) is a genetic disorder characterized by a decrease in endogenous insulin secretion, suggesting that exogenous insulin supplementation plays a central role in controlling glycemia." (PMID 39430732, 2024). "Permanent neonatal diabetes mellitus (PNDM) is a genetic disorder, characterized by a decrease in endogenous insulin secretion." (PMID 39430732, 2024).
pertussis (3 papers, 2021 to 2025). A contagious bacterial respiratory infection caused by Bordetella pertussis. "Early reports also described hypoglycemia in children with pertussis, and mean plasma-insulin levels were later found to be significantly increased in pertussis patients compared to controls." (PMID 34564627, 2021).
pituitary disease (3 papers, 2016 to 2024). "The diagnosis of GH deficiency was confirmed by the presence of pituitary disease and a peak GH secretion below 3 μg/L after an insulin tolerance test." (PMID 27472279, 2016). "Longitudinal comparison of insulin, glucose, cortisol and growth hormone concentrations in Controls (n=77) and Patients with history of pituitary disease (n=62) within each group." (PMID 39262672, 2024). "Comparative analysis of cortisol, growth hormone, glucose and insulin fluctuations between patients with a history of pituitary disease (n=62) and healthy controls (n=77) (Mann-Whitney U test)." (PMID 39262672, 2024). "Comparison of cortisol, growth hormone, glucose and insulin concentrations between patients with a history of pituitary disease (n=62) and Controls with an intact pituitary function (n=77)." (PMID 39262672, 2024).
plasma cell dyscrasia (3 papers, 2015 to 2026). "Given the sequence data and clinical expression of the anti-insulin antibody, the authors considered, hypothetically, that the autoreactive plasma cell that produced the anti-insulin antibody, initially, developed normally but later transformed into a plasma cell neoplasm." (PMID 26241232, 2015).
porphyria (3 papers, 2021 to 2023). Porphyria is a group of diseases in which substances called porphyrins build up, negatively affecting the skin or nervous system. "Given that it is an enhanced transcriptional pathway different from that activated during fasting, we decided to test the co-administration of glucose and exogenous insulin during acute attacks of porphyria induced by the administration of increasing doses of phenobarbital for four consecutive days." (PMID 33807619, 2021).
postpartum depression (3 papers, 2020 to 2024). A type of clinical depression that occurs after childbirth. "Second, the interactive contactless exercise lowered metabolic control and stress response factors (TG, Insulin, Leptin, and Cortisol) that contribute to postpartum depression." (PMID 38684812, 2024).
pregnancy toxemia (3 papers, 2010 to 2020). "Pregnancy toxemia is a condition that develops in near-term pregnant ewes related to insulin sensitivity." (PMID 33287449, 2020). "As gestation progresses, especially near term, insulin secretion and sensitivity decrease and can potentially contribute to cases of pregnancy toxemia." (PMID 33269340, 2020). "There were significant (P < .01) increase in both cortisol and insulin in pregnancy toxemic animals at 24 h and 36 h, respectively, after induction of pregnancy toxemia." (PMID 20613964, 2010). "From this study we can conclude that pregnancy toxemia might affect humoral immune responses as well as insulin, cortisol, and thyroid hormones." (PMID 20613964, 2010).
pressure ulcers (3 papers, 2015 to 2023). "There are case reports and studies on the usage of topical insulin on diabetic ulcers and decubitus ulcers." (PMID 37397672, 2023). "Notably, insulin treatment has been shown to improve wound healing in other types of wounds, such as burns and pressure ulcers, too." (PMID 33260645, 2020). "This resulted in patients not receiving medication (such as warfarin or insulin), having dressings unchanged, and surgical wounds or pressure ulcers left untended for days." (PMID 26622036, 2015).
protein deficiency (3 papers, 2011 to 2024). "Lower levels of mt-tRF-LeuTAA in β-cells are linked to reduced insulin secretion capacity in mice upon 16-hour fasting, in obese diabetic db/db mice, and in adult rats exposed to fetal and postnatal protein deficiency." (PMID 38704026, 2024). "Previous works with this model of protein deficiency in pregnancy and lactation have stated permanent changes in expression of liver enzymes involved in glucose homeostasis, increases of liver insulin sensitivity and reduction of glucose tolerance." (PMID 21637364, 2011). "Caloric restriction and protein deficiency can lead to IUGR and a reduction in β cell mass and function in rodents, possibly since fetal islets secrete insulin in response to amino acids." (PMID 35393955, 2022).
Respiratory insufficiency (3 papers, 2013 to 2021). "Post-operative respiratory insufficiency was not reported in any patient regardless of insulin administration." (PMID 25278226, 2014).
retinal detachment (3 papers, 2015 to 2024). An eye emergency condition which may lead to blindness if left untreated. "In mouse models of retinal detachment, subocular injections of insulin and insulin sensitizers such as metformin can attenuate the post-detachment inflammatory response and leukocyte infiltration associated with cone loss." (PMID 37191619, 2023).
selenium deficiency (3 papers, 2020 to 2024). A nutritional deficiency disease resulting from inadequate selenium levels in the body, which can lead to impaired function of selenoproteins essential for antioxidant defense and thyroid hormone metabolism. "Selenium deficiency impairs the function of selenoproteins, including glutathione peroxidases, which have been reported to influence regulation of enzymes in the insulin signalling cascade and glucose metabolism." (PMID 31968625, 2020). "Both animal and epidemiologic investigations have found that selenium deficiency is associated with decreased insulin sensitivity, which could be improved by appropriate supplementation." (PMID 37145256, 2024). "Dietary selenium deficiency resulted in similar effects on glucose tolerance and insulin secretion, with significant interactions between arsenic and dietary conditions in select insulin-related parameters." (PMID 34445052, 2021). "Selenium deficiency also decreased insulin levels at 2, 5, and 15 min following arginine injection." (PMID 34445052, 2021). "Selenium deficiency improved glucose tolerance, decreased fasting glucose and insulin, decreased glucose at the later time points of the IPGTT, and decreased insulin levels during the arginine stimulation test." (PMID 34445052, 2021). "The effects of arsenic on arginine-stimulated insulin secretion were not amplified by dietary selenium deficiency." (PMID 34445052, 2021). "Intriguingly, this was not the case in our model; rather, selenium deficiency itself partially recapitulated the effects of arsenic on glucose homeostasis and insulin secretory dynamics." (PMID 34445052, 2021). "Conversely, females exposed to selenium deficiency in utero exhibited increased plasma thyroxine levels with no change in plasma insulin." (PMID 31968625, 2020). "First, due to limited data from the US population, we could not figure out the whole picture reflecting the association between selenium concentration and insulin sensitivity since the population with selenium deficiency was not included." (PMID 37145256, 2024). "There was a significant effect modification between arsenic and selenium deficiency in which arsenic significantly affected fasting glucose and insulin under normal dietary conditions, and selenium deficiency significantly decreased these parameters in the absence of arsenic." (PMID 34445052, 2021).
short bowel syndrome (3 papers, 2012 to 2025). "It is quite possible as noted in the case reports of short bowel syndrome patients on TPN in the 1970’s that extreme chromium deficiency causes defects in insulin secretion and/or action." (PMID 23194380, 2012). "When monitoring changes in nutrient absorption, we measured blood glucose, insulin, glucagon, and amylin levels in patients with short bowel syndrome during a meal test." (PMID 40886373, 2025).
Simpson-Golabi-Behmel syndrome (3 papers, 2011 to 2022). Simpson-Golabi-Behmel syndrome is a rare X-linked multiple congenital anomalies syndrome, characterized by pre- and postnatal overgrowth, distinctive craniofacial features, variable congenital malformations, organomegaly and an increased tumor risk. "We characterized the insulin regulation of THRSP in vivo in human adipose tissue biopsies and in vitro in Simpson-Golabi-Behmel syndrome (SGBS) adipocytes." (PMID 35715726, 2022).
squamous cell lung carcinoma (3 papers, 2017 to 2025). A carcinoma arising from squamous bronchial epithelial cells. "We identified six hormone levels to be significantly associated with lung squamous cell carcinoma (LUSC): total testosterone, oestradiol, thyrotropin-releasing hormone, insulin, parathyroid hormone, and glucocorticoid." (PMID 40017690, 2025).
stomatitis (3 papers, 2015 to 2025). Inflammation of the oral mucosa due to local or systemic factors. "A total of 23 (46.9%) participants had a drug-related adverse event, most commonly decreased neutrophil count (n = 6, 12.2%), increased blood insulin (n = 5, 10.2%), and stomatitis (n = 5, 10.2%)." (PMID 40713644, 2025). "A total of 23 (46.9%) participants out of 49 had a drug-related adverse event, most commonly decreased neutrophil count (n = 6, 12.2%), increased blood insulin (n = 5, 10.2%), and stomatitis (n = 5, 10.2%)." (PMID 40713644, 2025). "Stomatitis, pneumonitis and impaired insulin secretion that are included in the label are usually reported in patients with Everolimus." (PMID 38533254, 2024).
teratoma (3 papers, 2012 to 2025). A non-seminomatous germ cell tumor characterized by the presence of various tissues which correspond to the different germinal layers (endoderm, mesoderm, and ectoderm). "Recent evidence indicates that murine VSELs are kept quiescent in adult tissues and protected from teratoma formation by epigenetic modification of imprinted genes that regulate insulin/insulin like growth factor signaling (IIS)." (PMID 22498452, 2012).
Tinnitus (3 papers, 2021 to 2024). Tinnitus is an auditory perception that can be described as the experience of sound, in the ear or in the head, in the absence of external acoustic stimulation. "Moreover, hyperinsulinaemia due to low insulin sensitivity contributes to the development of inner ear disturbances, which could explain the observed association with 10-year incidence of tinnitus." (PMID 34836381, 2021). "Similarly, our significant finding between lower cereal fibre intake and a 42% increase in tinnitus risk may also be due to reduced insulin sensitivity." (PMID 34836381, 2021).
Tremor (3 papers, 2009 to 2025). An unintentional, oscillating to-and-fro muscle movement about a joint axis. "In the high-fat fed groups, the insulin tolerance test was stopped at 60 min as some of the mice developed tremor." (PMID 19521513, 2009). "However, she discontinued the NPH insulin 2 years ago due to tremor and weakness following the injections; therefore, she has been injecting only 10 units of regular insulin once a day." (PMID 41235379, 2025).
Truncal obesity (3 papers, 2009 to 2018). Obesity located preferentially in the trunk of the body as opposed to the extremities. "Besides, centripetal obesity was a powerful stimulus for increasing the plasma insulin level and, therefore, it may increase the risk of HUA." (PMID 29720927, 2018).
tuberous sclerosis (3 papers, 2018 to 2022). Hereditary disease characterized by seizures, intellectual disability, developmental delay, and skin and ocular lesions. "The consequently released growth factors such as insulin and insulin-like growth factor (IGF) activate mTORC1 through phosphoinositide 3-kinase AKT-tuberous sclerosis-RHEB (PI3K-AKT-TSC-RHEB) signaling." (PMID 35215560, 2022). "Growth factors such as insulin and insulin-like growth factor (IGF) regulate mTORC1 through phosphoinositide 3-kinase (PI3K)-AKT-Tuberous sclerosis (TSC)-RHEB signaling." (PMID 30011848, 2018). "We then demonstrate that decanoic acid decreases mTORC1 activity in the absence of insulin and under high-glucose conditions in ex vivo rat hippocampus and in tuberous sclerosis complex (TSC) patient-derived astrocytes." (PMID 32879008, 2020).
type A insulin resistance syndrome (3 papers, 2020 to 2022). "Type A Insulin resistance syndrome (TAIRS) is an autosomal dominant or recessive genetic disorder caused by insulin dysfunction resulting from insulin receptor (INSR) gene mutation." (PMID 35634501, 2022).
Urinary incontinence (3 papers, 2014 to 2026). Loss of the ability to control the urinary bladder leading to involuntary urination. "Among the postmenopausal women, levels of insulin and HOMA-IR were significantly higher in those with incontinence and mean concentration of high-density lipoprotein was lower in those with incontinence." (PMID 26529410, 2015).
ventricular tachycardia (3 papers, 2019 to 2025). A disorder characterized by an electrocardiographic finding of three or more consecutive complexes of ventricular origin with a rate greater than a certain threshold (100 or 120 beats per minute are commonly used). "Immediate management included oxygen administration (3 L/min via reservoir mask), intravenous calcium gluconate, and insulin-glucose therapy (40 mL of 50% dextrose with four units of regular insulin), which resolved the ventricular tachycardia." (PMID 40525013, 2025).